UNC5D (unc-5 netrin receptor D)
Diseases named in the same sentence as UNC5D in open-access papers:
UNC5D is named in the same sentence as 42 diseases in open-access papers, as found by Europe PMC text mining. Sharing a sentence is not in itself a finding about the gene and the disease. The quoted sentences say what the papers report.
neuroblastoma (8 papers, 2017 to 2025). Neuroblastoma (NB) is the most common solid, extracranial childhood tumor. "Studies have shown that PCD induced by NGF deficiency in NGF-dependent human neuroblastoma cells, UNC5D emerges as a key player in this intricate regulatory network." (PMID 39186800, 2024). "Studies have shown an association of the UNC5D gene with kidney and bladder cancer and neuroblastoma." (PMID 29221192, 2017). "UNC5D, a newly added member of the Unc5 family, widely expressed in normal tissues, was frequently absent or attenuated in cancer cell lines and reported to be associated with multiple cancers including kidney cancer, neuroblastoma and bladder cancers." (PMID 29221192, 2017). "High levels of UNC5D mRNA expression exhibit a statistically significant correlation with good prognosis among neuroblastoma patients." (PMID 39186800, 2024). "Consistent with other members of this family, UNC5D has also been characterized as a tumor suppressor gene for several cancers, such as neuroblastoma, renal cell carcinoma, prostate cancer, and bladder cancer." (PMID 34922605, 2021). "Previously, UNC5D was found to be a tumor suppressor and frequently downregulated in primary renal cell carcinomas, neuroblastoma, bladder cancer and papillary thyroid cancer." (PMID 32629428, 2020). "Although the function of UNC5D is not yet completely clarified, previous studies have demonstrated that UNC5D expression was significantly higher in favorable neuroblastomas than in unfavorable ones, and higher UNC5D levels were correlated with longer survival time." (PMID 29221192, 2017).
bladder cancer (7 papers, 2016 to 2025). "UNC5D, a netrin receptor involved in apoptosis, was described as tumor suppressor gene in renal cell carcinoma and bladder cancer, and was shown to reside in a genetic locus predisposing to colon carcinoma in mice." (PMID 29682206, 2018). "This suggested that the role of UNC5D in bladder cancer may be associated with the ACOX family." (PMID 41407823, 2025). "Meanwhile, genetic analysis showed that allelic imbalance significantly inhibits the UNC5D gene in unstable bladder tumors and that UNC5D may have important roles as a novel suppressor in bladder cancer via the UNC5D/DAPK pathway." (PMID 29221192, 2017). "UNC5D may serve as a new inhibitor of bladder cancer through the UNC5D/DAPK pathway." (PMID 41407823, 2025).
colorectal cancer (6 papers, 2008 to 2025). A primary or metastatic malignant neoplasm that affects the colon or rectum. "Briefly, hypermethylation of TMEM176A is associated with metastasis and reduced overall survival in colorectal cancer while UNC5D is a novel putative metastatic suppressor gene shown to be commonly hypermethylated in prostate cancer." (PMID 34922619, 2021). "Subsequently, qRT-PCR assays were conducted on three colorectal cancer cell lines, namely HCT116, HT29 and SW480 cells, revealing a notable reduction in UNC5D mRNA expression levels in all three cell lines." (PMID 39186800, 2024). "Our scRNA-seq data revealed prominent expression of deleted in colorectal cancer (DCC) and DSCAM, and weaker expression of Unc5c, Unc5D, and Neogenin." (PMID 39569362, 2024).
renal cell carcinoma (5 papers, 2017 to 2025). "Low expression of UNC5D is significantly associated with poor prognosis of renal cell carcinoma, and loss of its expression may be a potential concomitant feature or regulatory factor of renal cell carcinoma." (PMID 41407823, 2025). "We previously showed that loss of heterozygosis and DNA methylation contributed to the inactivation of UNC5C and UNC5D in renal cell carcinoma." (PMID 34922605, 2021).
colon carcinoma (4 papers, 2017 to 2022). "A genome-wide associated study has identified UNC5D as one of candidate genes associated with colon cancer predisposition." (PMID 29221192, 2017). "To evaluate the role of O-GlcNAcylation in the epigenetic downregulation of the UNC5 family, we first examined the expression of UNC5A, UNC5B, UNC5C and UNC5D transcripts in the human colon cancer cell line HCT116." (PMID 33126652, 2020).
lung carcinoma (4 papers, 2013 to 2025). "For example, the UNC5D gene shows hypermethylation at its promoter and hypomethylation in downstream introns in lung cancer." (PMID 39991629, 2025). "Functional studies found that overexpression of UNC5D significantly decreased the cellular capacity to proliferate, migrate and invade the lung cancer cell line H1299, suggesting a tumor suppressor role of UNC5D." (PMID 32629428, 2020). "To clarify the function of UNC5D mutants, we analyzed the NCI-H1299 lung cancer cell line in vitro." (PMID 32629428, 2020).
breast carcinoma (3 papers, 2020 to 2025).
non-small cell lung carcinoma (3 papers, 2013 to 2023). A group of at least three distinct histological types of lung cancer, including non-small cell squamous cell carcinoma, adenocarcinoma, and large cell carcinoma. "Our previous study using multi-region sequencing also identified UNC5D as a significantly mutated gene in non-small-cell lung cancer and a late mutated event during tumorigenesis and progress." (PMID 29221192, 2017).
prostate carcinoma (3 papers, 2021 to 2024). A carcinoma that arises from epithelial cells of the prostate gland. "Moreover, down-regulated expression of UNC5D in prostate cancer due to the hypermethylation of promoter was involved in the distant metastasis of the disease." (PMID 34922605, 2021).
renal carcinoma (3 papers, 2016 to 2025). A carcinoma arising from the epithelium of the renal parenchyma or the renal pelvis. "Previous studies have indicated that hypermethylation of a CpG island in the promoter region together with loss of heterozygosity (LOH) may contribute to the UNC5D silencing in renal cancer." (PMID 29221192, 2017). "Recovery of UNC5D expression in renal cancer cells significantly inhibited cell proliferation, whereas the knockdown of UNC5D increased cell growth." (PMID 41407823, 2025). "UNC5D overexpression has been suggested to inhibit cell multiplication, migration and invasion in renal cancer cells by inducing cell cycle arrest at G2/M phase." (PMID 27846823, 2016). "In general, NTN1, NEO1, DSCAM, UNC5C, and UNC5D are all regulated by HDAC members in renal cancer, suggesting that NTN1, NEO1, DSCAM, UNC5C, UNC5D, and especially NEO1 and UNC5C may be essential for the regulation and outcome of renal cancer." (PMID 41407823, 2025). "Cell cycle analysis in our study showed that overexpressed UNC5D could induce G2-M cell-cycle arrest in thyroid cancer cells, which was similar to the results that have been reported in primary renal cancer cells." (PMID 29221192, 2017).
lymph node metastasis (2 papers, 2013 to 2017). "Lower UNC5D expression was significantly associated with aggressive tumor behaviors, such as lymph node metastasis and BRAF mutation." (PMID 29221192, 2017).
papillary thyroid cancer (2 papers, 2017 to 2020). "We investigated whether UNC5D acts as a tumor suppressor in papillary thyroid carcinoma (PTC)." (PMID 29221192, 2017). "First, UNC5D expression in papillary thyroid cancer versus adjacent noncancerous tissues was investigated, and the relationship between UNC5D and clinicopathological variates was explored." (PMID 29221192, 2017).
type 2 diabetes (2 papers, 2018 to 2022). "In contrast, UNC5D, ST3GAL6, SCG3, and IGFBP1, which are negatively affected by noisy workplace environments, are potentially protective factors against coronary heart disease (UNC5D), type 2 diabetes (UNC5D), tinnitus (ST3GAL6, SCG3), and rheumatoid arthritis (IGFBP1)." (PMID 35602164, 2022).
Diabetes (1 paper, 2022). "However, the mechanism of UNC5D expression in diabetes is still unclear." (PMID 35885938, 2022).
head and neck squamous cell carcinoma (1 paper, 2025). A squamous cell carcinoma that arises from any of the following anatomic sites: lip and oral cavity, nasal cavity, paranasal sinuses, pharynx, larynx, and salivary glands. "Six of the 11 predicted UNC5D fusion genes were destroyed at chr8:35406810, which included three in BLCA, two in BRCA, and one in head and neck squamous cell carcinoma (HNSC)." (PMID 41407823, 2025).
metastatic prostate carcinoma (1 paper, 2022). A carcinoma that arises from the prostate gland and has spread to other anatomic sites. "More and more attention has been paid to the inhibition of UNC5 receptor and its biological function in human malignant tumors, UNC5D could be a potential diagnostic biomarker and therapeutic target for metastatic prostate cancer (PCa)." (PMID 35885938, 2022).
osteosarcoma (1 paper, 2022). A usually aggressive malignant bone-forming mesenchymal neoplasm, predominantly affecting adolescents and young adults. "Another most interesting observation in our study is that a few of the hub genes of Rb tumors including CDK1, CDK2, CCNB1, HDAC1 and UNC5D are reported to play a key role in the pathogenesis of osteosarcoma, the most common secondary cancer in Rb patients." (PMID 35359459, 2022).
Rb (1 paper, 2022). "This unique overexpression of UNC5D gene in Rb tumor cells suggests that UNC5D might act as a novel and promising biomarker for the early diagnosis of retinoblastoma." (PMID 35359459, 2022). "However, the identification of JUN, PIK3CA, MAPK1 and UNC5D as hub genes in our study has thrown light on the role of inflammation, cell adhesion and cell proliferation in Rb tumors." (PMID 35359459, 2022). "Interestingly, the GEO2R and co-expression network analysis have identified three genes namely E2F3, ESR1, and UNC5D that are significantly deregulated by modified DNA methylation, mRNA and microRNA expression in Rb tumors." (PMID 35359459, 2022). "The expression of E2F3 and UNC5D were up-regulated and that of ESR1 was down-regulated in Rb tumor cells when compared to that in non-tumorigenic hTERT-RPE cells." (PMID 35359459, 2022).
renal clear cell carcinoma (1 paper, 2025). "For example, for renal clear cell carcinoma driven by UNC5D methylation, a combination protocol of “HDAC inhibitor (restoring UNC5D expression) + netrin-1 antibody” can be explored to simultaneously inhibit tumor proliferation and immune evasion." (PMID 41407823, 2025).
Sleep apnea (1 paper, 2023). An intermittent cessation of airflow at the mouth and nose during sleep is known as sleep apnea. "UNC5D is a netrin receptor involved in inflammation, cell adhesion, cell migration, and cell survival, that has been associated with sleep disturbance, sleep chronotype, and sleep apnea." (PMID 38046221, 2023).
thyroid cancer (1 paper, 2017). "Nevertheless, the clinicopathological data and the cellular functional data in the present study are sufficient to establish that UNC5D is a novel tumor suppressor gene in thyroid cancer and is associated with tumor aggressiveness." (PMID 29221192, 2017). "To assess the biological significance of UNC5D in thyroid cancer pathogenesis, we used a lentiviral-mediated UNC5D overexpression vector to effectively upregulate UNC5D expression in the PTC cell lines K1 and TPC-1." (PMID 29221192, 2017). "To determine whether UNC5D could inhibit the proliferation or migration of thyroid cancer cells, we used a lentivirus to build the UNC5D overexpression and negative control cell lines." (PMID 29221192, 2017). "The current study, which focused on the role of UNC5D, showed for the first time that UNC5D expression was frequently reduced or lost in PTC tumors and implied its important tumor suppressor function in thyroid cancer cells." (PMID 29221192, 2017).
tumor (13 papers, 2013 to 2026). "We further demonstrated that recurrent mutations of UNC5D in NSCLC lead to a loss of tumor suppressor function in vitro and in vivo." (PMID 32629428, 2020). "Mutations in UNC5D promoted tumorigenesis by abolishing the tumor suppressor function of the encoded protein." (PMID 32629428, 2020). "In summary, this is the first study that highlighted the tumor suppressor potential of UNC5D in PTC, which may serve as a potential diagnostic and therapeutic target for PTC intervention." (PMID 29221192, 2017). "Further importantly, UNC5D, a potent tumor suppressor gene whose protein expression is down-regulated in various cancer cells including HeLa, HCT116 and HuH cancer cells is found to be significantly up-regulated in Y79 and WERI-Rb-1Rb tumor cells." (PMID 35359459, 2022). "The potential of methylated UNC5C or UNC5D in circulating tumor DNA as biomarker for CRC should also be taken into consideration in future study." (PMID 34922605, 2021). "Among the tumor suppressor genes frequently epigenetically downregulated in CRC, the four related genes of the UNC5 family: UNC5A, UNC5B, UNC5C and UNC5D encode dependence receptors that regulate the apoptosis/survival balance." (PMID 33126652, 2020). "Consistent with the in vitro data, the growth of subcutis tumors expressing UNC5D-WT was inhibited, whereas tumors from cells overexpressing the UNC5D mutants had significantly larger tumor volumes (P < 0.05) that were similar to that of the vector control." (PMID 32629428, 2020). "Overexpression of UNC5D significantly suppressed malignant cell behaviors, including cell proliferation and migration, as well as tumor growth in vivo." (PMID 29221192, 2017). "We found that overexpression of UNC5D significantly decreased the cellular capacity to proliferate, suggesting a tumor suppressor role of UNC5D in opposing the malignant transformation of PTC." (PMID 29221192, 2017). "Consistent with in vitro results, UNC5D significantly inhibited tumor growth in vivo through decreased tumor volume and weight in mice (P< 0.05)." (PMID 29221192, 2017). "Conversely, genes related to epithelial differentiation and keratinization (FLG, FLG2, HRNR, TCHH, KRT73), immune regulation and tumor suppression (HLA-G, UNC5D), and metabolic signaling were downregulated, reflecting loss of tissue integrity and immune control." (PMID 41900972, 2026). "UNC5D is a well-known tumor suppressor gene, whose normal expression can inhibit tumor progression." (PMID 41179682, 2025). "After correction for age, tumor size, stage and grade, ER/PR/HER2 status and 3-gene classifier subtype, the loss of WRN (p=0.053; HR 1.2), DUSP26 (p=0.022; HR 1.3), UNC5D (p=0.026; HR 1.3), ZNF703 (p=0.026; HR 1.3) and FGFR1 (p=0.002; HR 1.5) still predicted worse DFS." (PMID 29682206, 2018). "Data thus acquired support a tumor-suppressive function of UNC5D in PTC." (PMID 29221192, 2017). "Furthermore, such tumor suppressor role has also been demonstrated for Unc5d." (PMID 34193044, 2021).
cancer (8 papers, 2017 to 2025). A tumor composed of atypical neoplastic, often pleomorphic cells that invade other tissues. "We found that NTN1, DCC, DSCAM, MCAM, and UNC5D were methylated in many cancers, of which UNC5D was the most prominent." (PMID 41407823, 2025). "Genes potentially associated with cell migration and cancer metastasis included CNTN5, FN1, Integrin Subunit Beta 6 (ITGB6), EPHB1, Unc-5 Netrin Receptor D (UNC5D), SDK1, RADIL, LRRC7, PCDH11X, and ADAMTS9." (PMID 39770638, 2024). "More importantly, UNC5D, a potent tumor suppressor gene in most cancers is significantly up-regulated in Y79 and Weri Rb1 cells, which, in turn, questions its anti-cancer properties." (PMID 35359459, 2022). "The co-methylation pattern with UNC5D was the most common cancer species." (PMID 41407823, 2025). "While acting as a tumor suppressor gene in most cancers, UNC5D might behave like an oncogene in Rb tumors." (PMID 35359459, 2022). "It was found that the overexpressed UNC5D could inhibit cell proliferation in these two PTC-derived cancer cell lines." (PMID 29221192, 2017). "Our study results suggest that UNC5D might act in a duplicitous manner in different cancer types." (PMID 35359459, 2022). "Further methylation and clinical analysis of LinkedOmics revealed that UNC5D showed hypermethylation and poor survival in KIRC, findings that correlated with its low expression and adverse prognosis in this cancer." (PMID 41407823, 2025). "Moreover, UNC5C and UNC5D transcripts remained undetectable upon OGT silencing (Decourcelle, A.; Dehennaut, V.; Université de Lille, CNRS, Inserm, CHU Lille, UMR9020-U1277—CANTHER—Cancer Heterogeneity, Plasticity and Resistance to Therapies, F-59000 Lille, France." (PMID 33126652, 2020).
neurodevelopmental disorder (1 paper, 2017). A behavioral and cognitive disorder with onset during the developmental period that involves impaired or aberrant development of intellectual, motor, or social functions. "A chromosomal breakpoint of apparently balanced chromosome rearrangements was identified in intron 5 of UNC5D in a family with neurodevelopmental disorders." (PMID 28754176, 2017).
psychiatric disorder (1 paper, 2018). A disorder characterized by behavioral and/or psychological abnormalities, often accompanied by physical symptoms. "The current study shows that multiple mutations previously linked to mental illness result in shared gene expression changes and decreased neurite outgrowth related to decreased UNC5D expression." (PMID 30410030, 2018). "Thus, two independent DISC1 mutations linked to major mental illness result in impaired neurite outgrowth via decreased expression of UNC5D, implicating this pathway in the pathogenesis of psychiatric disorders." (PMID 30410030, 2018).
UNC5D also shares sentences with these, for which no sentence is quoted: adenocarcinoma (1 paper); bladder tumors (1); cervical cancer (1); chondrosarcoma (1); coronary heart disease (1); endometrial cancer (1); endometriosis (1); infection (1); intrauterine growth restriction (1); iron deficiency (1); Obesity (1); rheumatoid arthritis (1); skin melanoma (1); squamous cell carcinoma (1); stomach cancer (1); Tinnitus (1); uterine cancer (1).